PSME3 (proteasome activator subunit 3)
Description:
Subunit of the 11S REG-gamma (also called PA28-gamma) proteasome regulator, a doughnut-shaped homoheptamer which associates with the proteasome. 11S REG-gamma activates the trypsin-like catalytic subunit of the proteasome but inhibits the chymotrypsin-like and postglutamyl-preferring (PGPH) subunits. May also be involved in cell cycle regulation. Mediates CCAR2 and CHEK2-dependent SIRT1 inhibition.
Synonyms: REG-gamma; PA28g; PA28gamma; Ki; PA28-gamma; HEL-S-283
Tractability: PROTAC: ubiquitination databases record sites on it; its protein half-life has been measured.
Gene: Protein-coding gene on chromosome 17 (42,824,385 to 42,843,760, forward strand). Ensembl gene ENSG00000131467.
Subcellular location: Nucleus; Cytoplasm
Subcellular location (Human Protein Atlas): Nucleoplasm; Basal body; Cytosol; Primary cilium
Pathways (Reactome):
Metabolism of proteins: Proteasome assembly
Gene Ontology:
Molecular function: endopeptidase activator activity; identical protein binding; MDM2/MDM4 family protein binding; protein binding
Biological process: negative regulation of extrinsic apoptotic signaling pathway; regulation of proteasomal protein catabolic process; apoptotic process; flagellated sperm motility; regulation of G1/S transition of mitotic cell cycle; response to oxidative stress
Cellular component: membrane; nucleoplasm; nucleus; proteasome complex; cytosol; proteasome storage granule; cytoplasm; proteasome activator complex
Genetic constraint (gnomAD): Loss-of-function variants: 7 observed, 38.47 expected, observed/expected ratio (o/e) 0.18, 90% interval 0.1 to 0.34. The upper end of that interval is the gene's LOEUF score, 0.34, which puts it in group 1 of 6, group 1 being the genes least tolerant of losing a copy. Missense variants: 187 observed, 308.52 expected, observed/expected ratio (o/e) 0.61, 90% interval 0.54 to 0.68. Synonymous variants: 106 observed, 108.9 expected, observed/expected ratio (o/e) 0.97, 90% interval 0.83 to 1.14.
Homologues: Orthologues: mouse Psme3 (100% identical), guinea pig PSME3 (99% identical), chimpanzee PSME3 (95% identical), dog PSME3 (95% identical), macaque PSME3 (95% identical), pig PSME3 (95% identical), rabbit PSME3 (94% identical), tropical clawed frog psme3 (83% identical), zebrafish psme3 (80% identical), Caenorhabditis elegans psme-3 (49% identical), Drosophila melanogaster REG (48% identical). Paralogues in human: PSME1 (41% identical), PSME2 (34% identical).
Diseases named in the same sentence as PSME3 in open-access papers:
PSME3 is named in the same sentence as 79 diseases in open-access papers, as found by Europe PMC text mining. Sharing a sentence is not in itself a finding about the gene and the disease. The quoted sentences say what the papers report.
breast carcinoma (16 papers, 2014 to 2025). "Proteasome activator subunit-3 (PSME3), a protein encoded by the PSME3 gene, was reported to be upregulated in breast cancer and it promotes protein proteolysis." (PMID 31877708, 2019). "Here, we found four upregulated hub genes (RPSA, SEC61A1, ITGB1, PSMB5) and three downregulated hub genes (PSME3, SNRNP70, SRSF3) that are significantly associated with poor overall survival of breast cancer patients." (PMID 36293493, 2022). "Aberrant overexpression of PSME3 has been revealed in a plethora of cancers, including pancreatic cancer, thyroid carcinoma, breast cancer, melanoma, oral cancer, non-small-cell lung cancer, and multiple myeloma." (PMID 34750284, 2022). "PSME3 is significantly up-regulated in breast cancer and in OSCC and plays an essential role in tumorigenesis." (PMID 34650966, 2021). "Knockdown of the PSME3 gene in human breast cancer cells, suppressed the proliferation of these cells and induced apoptosis." (PMID 31877708, 2019). "It should also be noted that a higher expression of PSME3 had been observed in several types of human cancers and this was found to be a marker of prognosis in breast cancer." (PMID 31877708, 2019). "Recently, proteasome activator subunit 3 (PSME3) has been shown to induce epithelial-mesenchymal transition of breast cancer cells together with induction of CSC marker expression and further to influence the tumor immune microenvironment." (PMID 30405720, 2018). "In addition, abnormally high expression of PSME3 protein was reported in breast cancer metastatic lymph nodes." (PMID 31877708, 2019). "Additionally, our observations indicated that the expression levels of PSME3 can predict the response to immunotherapy with PDL1 and CTLA4 in gastric adenocarcinoma and breast cancer in mouse models." (PMID 38312840, 2024). "For example, Proteasome Activator Subunit 3 (PA28γ) which promotes cell cycle progression has been shown to be directly targeted by miR-7 in the hamster ovarian cell line CHO, non-small cell lung cancer (NSCLC) and breast cancer via its 3′-UTR." (PMID 26308064, 2015). "Similarly, several studies have recently reported that PSME3 was overexpressed in breast cancer (BRCA) tissues compared to normal tissues and that BRCA patients with low expression levels of PSME3 had a favorable prognosis compared to patients with higher expression of PSME3." (PMID 34650966, 2021).
colorectal cancer (8 papers, 2014 to 2024). A primary or metastatic malignant neoplasm that affects the colon or rectum. "Nevertheless, high PSME3 expression has been previously associated with worse survival in colorectal cancer; our data confirm that PSME3 may also be important as a prognostic and predictive biomarker for other types of cancer." (PMID 36123629, 2022). "PSME3 is significantly overexpressed in colorectal cancer tissue compared with healthy donor tissue, leading to its consideration as a novel serum tumor marker for identifying colorectal cancer patients." (PMID 34650966, 2021). "Through suppressing cyclin B1 expression, proteasome activator complex subunit 3 (PSME3) triggers cell cycle arrest at the G2/M phase and enhances the radiosensitivity of colorectal cancer cells." (PMID 34462422, 2021). "Genes such as PSME3 and HSPD1 were involved in the pathogenesis of many cancer types such as colorectal cancer and colon cancer, but these genes may be important for the growth of GBM." (PMID 31137733, 2019).
systemic lupus erythematosus (8 papers, 2012 to 2024). An autoimmune multi-organ disease typically associated with vasculopathy and autoantibody production. "REGgamma (REGγ), also known as PSME3, or PA28gamma, was first discovered in the sera of systemic lupus erythematosus patients and identified as the Ki antigen." (PMID 28969047, 2017). "REGγ, also known as PA28gamma, 11Sgamma, or PSME3, was first identified as Ki antigen, a nuclear protein targeted by autoantibodies found in sera of patients with systemic lupus erythematosus." (PMID 22361172, 2012). "REGγ, also named Ki antigen, PSME3, PA28γ, or 11Sγ, was first found in the serum of patients with systemic lupus erythematosus and could regulate proteolysis in a ubiquitin-independent pathway by activating the 20S proteasome." (PMID 39536082, 2024).
pancreatic cancer (7 papers, 2020 to 2025). "In pancreatic cancer, PSME3 targets the cellular myeloma oncogene (c-Myc) to stimulate lactate secretion." (PMID 39346927, 2024). "In pancreatic cancer, PSME3 targets the cellular myeloid tumor (C-Myc) gene to stimulate lactate secretion." (PMID 39346927, 2024). "Meanwhile, a high expression of PSME3 was positively correlated with tumor size and negatively correlated with favorable prognosis in patients with pancreatic cancer." (PMID 34650966, 2021). "In addition, O-GlcNAcylation stabilizes Sirtuin 7 by inhibiting its interaction with proteasome activator subunit 3, and promotes pancreatic cancer progression." (PMID 40416363, 2025). "Immunohistochemistry experiments showed that PSME3 was highly expressed in pancreatic cancer cells." (PMID 35270630, 2022). "It has been reported that PSME3 plays oncogenic roles in pancreatic cancer by mediating c-Myc degradation to accelerate glycolysis and might act as a new therapeutic target for pancreatic cancer." (PMID 34650966, 2021). "In addition, PSME3 was significantly up-regulated in pancreatic cancer tissues and cell lines at both the mRNA and protein levels." (PMID 34650966, 2021). "Overexpression of PSME3 in cancers influences the stability of CMYC, however the published results are contradictory: high levels of PSME3 inhibited CMYC degradation in pancreatic cancer cells, whereas studies performed in cell lines showed that PA28γ promotes CMYC degradation." (PMID 32545208, 2020).
Huntington disease (5 papers, 2015 to 2024). Huntington disease (HD) is a rare neurodegenerative disorder of the central nervous system characterized by unwanted choreatic movements, behavioral and psychiatric disturbances and dementia. "Consequently, improving UPS activities by the overexpression of PA28γ (PSME3) recovers proteasome activities and bolsters cell survival of Huntington's disease-patient derived neurons." (PMID 26557146, 2015).
lung carcinoma (4 papers, 2021 to 2025). "Furthermore, we find associations between PSME3 expression and tumor staging as well as metastasis in kidney, liver, and lung cancers." (PMID 38312840, 2024). "In contrast, NFKBIA, PSME3, SPARCL1, CCL15, and APOA1 did not return established entries under these filters and at the time of query, indicating that, within IPA, they are not currently categorized as clinical lung cancer biomarkers." (PMID 41465234, 2025).
viral infection (4 papers, 2020 to 2024). "This SUMO1/PSME3/20S proteasome–involved proteolytic pathway has been known to be implicated in viral infection and replication." (PMID 36706181, 2023).
lung adenocarcinoma (3 papers, 2021 to 2024). A carcinoma that arises from the lung and is characterized by the presence of malignant glandular epithelial cells. "The Wang and others report PSME3 promotes lung adenocarcinoma development by regulating the TGF-β/SMAD signaling pathway." (PMID 39346927, 2024). "To investigate the specific mechanism by which PSME3 affects lung adenocarcinoma, we detected that p-AKT was down-regulated after knockdown of PSME3 by Western Blot assay, suggesting that PSME3 is involved in the regulation of these pathways." (PMID 39346927, 2024). "In conclusion, knockdown of PSME3 significantly inhibited cell proliferation, migration and invasion, and promoted apoptosis of lung adenocarcinoma cells." (PMID 39346927, 2024). "To further confirm the association between PSME3 and immune checkpoints, we conducted flow cytometry analysis after modulating PSME3 expression in 293T cells and silencing PSME3 in liver cancer Hut7, lung adenocarcinoma A549, and bladder cancer T24 cells." (PMID 38312840, 2024). "In conclusion, we found that PSME3 has been little studied in lung adenocarcinoma and may be a novel prognostic factor in lung adenocarcinoma." (PMID 39346927, 2024). "And Bcl-2 was down-regulated and cleaved PARP was up-regulated after knocking down PSME3, suggesting that PSME3 may affect the apoptotic process of lung adenocarcinoma through the PI3K/AKT pathway." (PMID 39346927, 2024). "and investigated PSME3, which may affect apoptosis in lung adenocarcinoma cells through the PI3K/AKT/Bcl-2 signaling pathway." (PMID 39346927, 2024). "Therefore, we followed up with a series of cellular experiments on PSME3 in lung adenocarcinoma." (PMID 39346927, 2024). "In addition, further animal experiments are needed to explore the functional role of PSME3 in lung adenocarcinoma, which could help to provide stronger clues to guide clinical application." (PMID 39346927, 2024). "Our research revealed abnormal expression levels of PSME3 in various cancer types and unveiled a correlation between high PSME3 expression and adverse clinical outcomes, especially in cancers like liver cancer (LIHC) and lung adenocarcinoma (LUAD)." (PMID 38312840, 2024). "By differential expression analysis and LASSO logistic regression analysis we constructed an 8-gene (IKBKB, LTBR, MIF, PPARD, PPIA, PSME3, S100A6, SEMA4B) based risk score model to predict lymph node metastasis in lung adenocarcinoma." (PMID 34109216, 2021).
rheumatoid arthritis (3 papers, 2014 to 2025). A chronic, systemic autoimmune disorder characterized by inflammation in the synovial membranes and articular surfaces. "Proteasome activator 28γ (PA28γ, also known as Ki antigen, REGγ, PSME3) is a proteasomal activator in the 11S family that is implicated in several cancers and rheumatoid arthritis where it is found to be overexpressed." (PMID 35714770, 2022). "Immune pathways were also enriched: Role of Osteoclasts in Rheumatoid Arthritis (FDR = 5.88 × 10−3; MMP12, ADAM9, NFKBIA), T-cell receptor and Interleukin-1 signaling (both FDR = 8.83 × 10−3; NFKBIA, PSME3)." (PMID 41465234, 2025).
amyotrophic lateral sclerosis (2 papers, 2023 to 2024). Amyotrophic lateral sclerosis (ALS) is a neurodegenerative disease characterized by progressive muscular paralysis reflecting degeneration of motor neurons in the primary motor cortex, corticospinal tracts, brainstem and spinal cord. "Moreover, cold-induced PA28γ/PSME-3 diminishes protein aggregation in C. elegans models of age-related diseases such as Huntington’s and amyotrophic lateral sclerosis." (PMID 37118550, 2023).
multiple myeloma (2 papers, 2022 to 2024). "PSME3 was also overexpressed in relapsed/refractory myelomas and correlated with poor prognoses." (PMID 39619148, 2024).
thyroid cancer (2 papers, 2022 to 2024). "Previous reports have also mentioned the abnormal expression of PSME3 in various types of cancer, including thyroid cancer, head and neck cancer, and osteosarcoma, which is consistent with our research findings." (PMID 38312840, 2024). "Only two cancer types, kidney chromophobe (KICH) and thyroid carcinoma (THCA), exhibit lower PSME3 gene expression when compared to normal tissues." (PMID 38312840, 2024).
cervical cancer (1 paper, 2025). A primary or metastatic malignant neoplasm involving the cervix. "For example, proteasome activator subunit 3 (PSME3) promotes DNA repair in cervical cancer cells by upregulating glycolytic proteins, whereas PSME3 knockdown impairs glycolysis and elevates radiosensitivity." (PMID 41441035, 2025).
fungal infections (1 paper, 2022). "The PSME3-deficient mice lessened numbers of CD8+ T cells and showed reduced clearance of fungal infections in the lungs." (PMID 35799836, 2022).
gastric cancer (1 paper, 2024). A primary or metastatic malignant neoplasm involving the stomach. "However, in gastric cancer STAD, high PSME3 expression was correlated with better OS." (PMID 38312840, 2024).
liver cancer (1 paper, 2024). An epithelial or non-epithelial malignant neoplasm that arises from the liver. "We also conducted preliminary validations of the impact of PSME3 on cell proliferation and wound healing in liver cancer." (PMID 38312840, 2024). "Meanwhile, we conducted independent survival prognosis analyses in TCGA and ICGC databases to further confirm the predictive capacity of high PSME3 expression for a poorer prognosis in liver cancer patients." (PMID 38312840, 2024). "Finally, through experimental validation, we confirmed the impact of PSME3 on liver cancer cell proliferation and wound healing, further supporting its biological function in liver cancer." (PMID 38312840, 2024). "Finally, we conducted initial validation of the general functions of PSME3 in liver cancer." (PMID 38312840, 2024). "Our previous findings indicate a close correlation between high PSME3 expression and the progression and prognosis of LIHC, with a significant role in liver cancer immunity." (PMID 38312840, 2024). "The independent prognostic value of PSME3 in LIHC was validated, underscoring its significance in assessing the prognosis of liver cancer patients." (PMID 38312840, 2024). "Additionally, PSME3 has been confirmed as an independent prognostic factor in LIHC, impacting not only immune regulation but also aspects like liver cancer cell proliferation and wound healing." (PMID 38312840, 2024).
male infertility (1 paper, 2022). The inability of the male to effect fertilization of an ovum after a specified period of unprotected intercourse. "PSME3, PSMD3, and CDC27 were the top 3 hub genes identified within the male infertility network." (PMID 35918717, 2022).
renal cell carcinoma (1 paper, 2018). "KEGG pathway analysis revealed that REGγ (PSME3) upregulation is closely correlated with renal cell carcinoma." (PMID 29795381, 2018).
sarcoidosis (1 paper, 2017). Sarcoidosis is a multisystemic disorder of unknown cause characterized by the formation of immune granulomas in involved organs. "The immunoproteasome gene PA28γ (also known as PSME3) that encodes the gamma subunit of 11 S regulator of immunoproteasome was downregulated in sarcoidosis monocytes." (PMID 28577019, 2017).